TPO (thyroid peroxidase)
Diseases named in the same sentence as TPO in open-access papers (continued):
Sharing a sentence is not in itself a finding about the gene and the disease.
Hashimoto thyroiditis (continued). "Case 4 had hyperthyroidism due to Hashimoto’s thyroiditis only 1 month after he was diagnosed to have chronic GVHD, his and his donor’s anti-TPO antibody and anti-thyroglobulin antibody were positive." (PMID 26777050, 2015). "Thyroid peroxidase (TPO) catalyses the biosynthesis of thyroid hormones and is a major autoantigen in Hashimoto’s disease—the most common organ-specific autoimmune disease." (PMID 26623656, 2015). "TSH-RA is a sensitive test for Graves' disease and Hashimoto's thyroiditis, which have a high prevalence of TGA and TPO-Ab, and normal healthy controls have only a 2%–4% prevalence of thyroid autoantibodies." (PMID 25478208, 2014). "Up to 20% of patients with T1DM have positive anti-thyroid antibodies; anti-thyroglobulin (anti-Tg) and anti-thyroid peroxidase (anti-TPO) antibodies and 2 to 5% of patients with T1DM develop autoimmune hypothyroidism." (PMID 22029731, 2011). "Autoantibodies (aAbs) against TPO, a common denominator of AITD, are present in 90% of Hashimoto's thyroiditis and 75% of Graves' disease patients' sera." (PMID 15769293, 2005). "We observed a significant positive correlation between both CRTP-4 and CTRP-12 levels and anti-TPO, suggesting that increased CTRP-4 may be tied to pro-inflammatory conditions in Hashimoto’s thyroiditis." (PMID 40060227, 2025). "While anti-TPO antibodies are present in all patients with Hashimoto’s thyroiditis, they are not believed to play a role in pathogenesis and are instead useful diagnostic markers." (PMID 40777071, 2025). "Elevated levels of thyroid peroxidase antibodies (anti-TPO), commonly seen in Hashimoto's thyroiditis, suggest that immune-mediated processes may possibly affect the central nervous system and the balance of neurotransmitters, causing psychiatric disturbances." (PMID 39539911, 2024). "Hashimoto’s thyroiditis is characterized by elevated thyroid-stimulating hormone (TSH), anti-thyroid peroxidase (TPO-Ab), and anti-thyroglobulin (Tg-Ab) antibodies, accompanied by lymphocytic and plasmacytic infiltration of the thyroid parenchyma and the destruction of thyroid follicles." (PMID 40071251, 2024). "In addition, the presence of elevated anti-TPO and anti-TSH antibodies is also suspicious for both Grave’s disease and Hashimoto’s thyroiditis." (PMID 39188503, 2024). "Anti-thyroid peroxidase antibody (anti-TPO), anti-thyroglobulin (anti-TG), thyroid stimulating hormone(TSH), thyroxine(sT4) levels and family history of Hashimoto's thyroiditis were screened at the study visit both in patients with jSLE and in healthy subjects." (PMID 37848930, 2023). "The authors reported a significantly higher frequency of anti-TPO and Hashimoto’s thyroiditis in cases than in the control group, without any additional effect induced by the CagA status." (PMID 37568552, 2023). "Hashimoto’s thyroiditis is T cell mediated rather than antibody mediated and the clinically measured thyroid antibodies to thyroglobulin and thyroid peroxidase are secondary to the tissue damage (and hence are polyclonal)." (PMID 35909553, 2022). "The test result for the presence of the H. pylori antibody was negative, and that for thyroid peroxidase (TPO) antibody was positive due to the patient’s Hashimoto’s disease." (PMID 33566307, 2021). "In Pearson’s correlation test, positive correlation was found between lymphocytic thyroiditis and preoperative TSH (r=0.161, p=0.010), anti-TPO (r=0.262, p=0.000), and preoperative anti-TG (r=0.171, p=0.016) values, but negative correlation was found with age (r=–0.152, p=0.015)." (PMID 35317375, 2021). "Green coffee, green tea, cumin, and mustard contain potentially bioaccessible TPO activators that also act as effective LOX inhibitors, which may point to their potentially health-promoting effects for people suffering from Hashimoto’s disease." (PMID 31671724, 2019).
Hashimoto thyroiditis (continued). "In Hashimoto's thyroiditis, however a small subset of patients (10%) are reported with clinically evident disease, and a negative serum anti-TPO-Ab." (PMID 31428301, 2019). "Although the role of B cells in development of Hashimoto’s thyroiditis is not as significant as in GD, it should be mentioned that they produce autoantibodies to the thyroglobulin (Tg) and thyroid peroxidase (TPO), which are thyroid self-antigens." (PMID 29449887, 2018). "Human autoimmune thyroid disease (AITD) is an organ-specific immune disease characterized by autoantibodies, such as anti-thyroglobulin (Tg) antibody, anti-thyroperoxidase (TPO) antibody and anti-TSH receptor (TSHR) antibody, mainly involving Hashimoto’s thyroiditis (HT) and Graves’ disease (GD)." (PMID 25429429, 2014). "Subjects with Graves disease often exhibit detectable TPO and/or TG antibodies (which are then nonspecific markers of Hashimoto thyroiditis), although the most commonly detectable thyroid autoantibodies in autoimmune hyperthyroidism are TSI." (PMID 25114812, 2014). "No patients were diagnosed histologically with Hashimoto's thyroiditis, although four patients showed increased TPO-ab > 60 kU/L (14.3%)." (PMID 24959372, 2014). "Given that our 2 patients had goiter and positive TPO antibodies and no drug or high iodine exposure history, they most likely had autoimmune hypothyroidism." (PMID 22551356, 2012). "Aside from the unexpected observation of the high prevalence of Hashimoto thyroiditis by cytology, especially in euthyroid patients, the lack of cytological correlation with TPO autoantibody positivity is noteworthy." (PMID 21172028, 2010). "None of the anti-TPO nor anti-TG positive patients in group A had signs or symptoms of Hashimoto's thyroiditis." (PMID 21188205, 2010). "However, a major question remains: What is the clinical significance of the anti-TPO aAbs which are present in the two well characterized AITD (Graves' disease and Hashimoto's thyroiditis)?" (PMID 15769293, 2005). "Same trend was observed in the recent study conducted on the prevalence of thyroid diseases in eight cities of India and presence of anti-TPO antibodies was shown to be conclusive for the disease; however that study has not reported prevalence of autoimmune hypothyroidism in particular." (PMID 26963610, 2016). "Two of the controls were found to have subclinical autoimmune hypothyroidism based on increased levels of TSH (4.3 and 11.5 mU/L) combined with a decreased level of thyroxine in one case (6.4 pmol/L), as well as positive levels of anti-thyroid peroxidase antibodies in both cases." (PMID 20137075, 2010). "However, our study found that neonates of mothers with positive TPO antibody had lower TSH levels and higher FT4 levels, which may due to the attack of TPO antibody to neonatal thyroid gland as Hashimoto thyroiditis and this needs to be confirmed in a large-scale study." (PMID 40678318, 2025). "Besides, whether participants had Hashimoto's thyroiditis was obtained through standardized questionnaires, yet not all participants underwent testing for TPO and TG antibodies." (PMID 38712310, 2024). "The thyroid peroxidase (TPO) test was also negative, thereby excluding a chronic lymphocytic thyroiditis." (PMID 26245479, 2015). "Moreover, women comprised a higher proportion of patients with Hashimoto’s thyroiditis than those without, who had lower serum levels of TSH, thyroglobulin, and TPO antibody (p < 0.05)." (PMID 40496557, 2025).
thyroid (321 papers, 2004 to 2026). "Thyroid-related adverse events are often associated with the presence of thyroid autoantibodies, such as anti-thyroglobulin (TG) and anti-thyroid peroxidase (TPO), prior to ICI therapy." (PMID 39859105, 2025). "The results of this study demonstrate a significant association between elevated TPO-Ab and an increased risk of miscarriage and postpartum thyroiditis in euthyroid women." (PMID 41503315, 2025). "Up to 50% of women with anti-TPO antibodies in early pregnancy will develop postpartum thyroiditis, making it a useful marker in identifying those at risk." (PMID 37868409, 2023). "Of note, while some of these autoantibodies are present in the serum of many individuals with normal thyroid function, the presence of TPO is significantly associated with thyroid disease." (PMID 35572553, 2022). "Some studies have suggested that thyroiditis has a protective effect; however, our results demonstrate that patients with higher TPO antibody levels preoperatively tend to have a lower risk of prognosis." (PMID 36277684, 2022). "Two independent Swedish studies demonstrated that patients with DMab-associated T1D had a higher risk of anti-CCP positive RA and of anti-thyroid peroxidase and anti-thyroglobulin positive thyroiditis." (PMID 36429105, 2022). "Due to the strong association between TPO antibodies and future thyroid disease, clinical screening and checking thyroid function at least once during gestation, during puerperium or one year postpartum are recommended." (PMID 34946265, 2021). "For these pregnant women at high risk for thyroid disease the ATA recommends TSH levels be measured with a reflex anti-TPO antibody if TSH is 2.5–10 μIU/ml." (PMID 34589452, 2021). "Although the TPO gene was identified to be associated with thyroid cancer and many other thyroid disorders, how TPO influences the risk of TC is still unclear." (PMID 34209805, 2021). "The presence of TPO in thyroid cell-secreted exosomes has been demonstrated recently, as well as the association of circulating TPO(+) vesicles with thyroid gland disorders." (PMID 32824820, 2020). "The associated anti-thyroid drugs share a common target, thyroid peroxidase, in their normal mechanism of action." (PMID 32027661, 2020). "For instance, in this study we demonstrated that the association between TPO and thyroid disease appears to be dependent on using expression data derived from thyroid tissue." (PMID 31924771, 2020). "Autoimmune thyroid disorders are predominantly associated with the presence of thyroid autoantibodies directed to TPO and thyroglobulin." (PMID 28575127, 2017). "Serum 25(OH)D concentrations <125 nmol/L were associated with an increased risk of thyroid disease, a 115% increased risk of elevated anti-TG antibody, 118% increased risk of anti-TPO antibody and 107% increased risk of elevated TSH." (PMID 29067607, 2017). "The most prevalent mutation is the c.1978C>G which represents 80 % of the total detected TPO mutations which express the importance of this mutation in thyroid disorders." (PMID 24482635, 2014). "Such genotoxicity was also detected as mutations in TPO and TG genes among Iraqi thyroid disorders patients." (PMID 24829552, 2014). "The presence of thyroid peroxidase antibodies (TPO-Ab) before treatment was identified as a risk factor for the incidence of thyroid disease in 60% of HCV patients receiving IFN α." (PMID 23383326, 2013). "In contrast, thyroiditis developed in Lo-expressor transgenics in association with autoantibodies to Tg in all mice and autoantibodies to TPO in some animals." (PMID 22970131, 2012). "Additionally, anti-thyroid peroxidase (anti-TPO) and IgA anti-tissue transglutaminase (anti-tTG-IgA) antibodies can detect coexisting autoimmune conditions such as thyroiditis and celiac disease, commonly associated with T1DM." (PMID 41008668, 2025).
thyroid (continued). "EAT caused thyroiditis follicle destruction and interfollicular lymphocyte infiltration in mice, increased concentrations of circulating thyroid autoimmune antibodies TG-Ab and TPO-Ab, and abnormal thyroid hormone levels." (PMID 39949783, 2025). "A strong association with family history of thyroid disease and a higher prevalence of anti-thyroid peroxidase (anti-TPO) antibody positivity further supports the role of underlying genetic and autoimmune mechanisms in the manifestation of thyroid dysfunction among women with GDM." (PMID 41473631, 2025). "Thus, positive TG and TPO antibodies at baseline are associated with a higher risk of developing destructive thyroiditis due to immune checkpoint inhibitor therapy." (PMID 37251665, 2023). "This congenic strain, named NOD-H2h4, carries the thyroiditis susceptible k allele at the MHC class II A locus (Kk, Ak, E0, Db), and develops a chronic, lymphocyte rich form of thyroiditis associated with the development of Tg antibodies (Abs) and then TPO Abs." (PMID 36077831, 2022). "Therefore, in this retrospective study, we aimed to investigate the associations of thyroid function indicators (FT4, TSH, and TPO Ab) and thyroid disorders with the occurrence of GDM in Chinese pregnant women." (PMID 35189861, 2022). "Environmentally relevant maternal levels of PCBs are associated with an increase in maternal TPO Ab implying that clinical thyroid disease later in life in a significant proportion of women might be attributable to PCBs." (PMID 34589452, 2021). "Although in the presence of thyroid-related symptoms or aberrant thyroid hormone levels, determination of TPO-abs might be important as part of the clinical diagnostic work-up." (PMID 28108944, 2017). "Interestingly, the authors noted that “none of the patients had autoimmune diseases,” even though three of them tested positive for anti-TPO, which could potentially indicate a heightened susceptibility to thyroid-related conditions in the future." (PMID 38397367, 2024). "Because TPO-Ab positivity itself could be diagnostic of thyroid disease, it could make some bias." (PMID 35379219, 2022). "Anti-thyroid peroxidase (anti-TPO) and anti-thyroglobulin (anti-TG) antibodies are the most frequently detected thyroid autoantibodies in chronic spontaneous urticaria, particularly among patients with the type IIb (autoimmune) endotype." (PMID 41608596, 2026). "Anti-TPO positivity and family history of thyroid disease emerged as independent predictors, underscoring the autoimmune contribution to thyroid impairment in GDM." (PMID 41473631, 2025). "The incidence of postpartum thyroiditis was significantly higher in women with elevated TPO-Ab levels (50.0% vs. 21.6%, p=0.001)." (PMID 41503315, 2025). "Family history of thyroid disorder (41.7% vs 12.9%; p = 0.012) and anti-TPO positivity (33.3% vs 5.4%; p = 0.003) were strongly associated." (PMID 41473631, 2025). "All patients tested positive for autoimmune markers, with one showing hypergammaglobulinemia and three testing positive for thyroid autoantibodies–anti-TPO, anti-thyroglobulin (anti-TG), and anti-thyroid receptor." (PMID 40740211, 2025). "Anti-TPO antibodies are more prevalent than anti-Tg antibodies and are more indicative of thyroid disease." (PMID 40937419, 2025). "We analyzed serum thyroid biomarkers, including serum vitamin D, anti-thyroglobulin (TG) antibody, and anti-thyroid peroxidase (TPO) antibody for patients with HT." (PMID 41113708, 2025). "Anti-thyroid antibodies, including anti-thyroperoxidase (TPO) and anti-thyroglobulin (TG) antibodies, have also been implicated in RSA." (PMID 39859499, 2025). "Anti-TPO antibody levels, an autoimmune thyroid marker, showed smaller but consistent reductions of 9–14%, suggesting modest improvement in subclinical autoimmune activity." (PMID 41465826, 2025). "Regarding the thyroid antibodies, 55.22% of children had positive anti-TPO Abs and 43.28% had positive anti-TG Abs." (PMID 41044753, 2025).
thyroid (continued). "On multivariate analysis, anti-TPO positivity (aOR 6.78; p = 0.016) and familial thyroid history (aOR 4.12; p = 0.047) independently predicted dysfunction." (PMID 41473631, 2025). "A family history of thyroid disease can increase the likelihood of elevated TPO-Ab levels in young women." (PMID 40927297, 2025). "Our patient's subclinical thyroiditis, evidenced by elevated anti-TPO levels and heterogeneous thyroid ultrasound findings, aligns with existing literature and highlights the broader autoimmune potential of untreated Lyme disease." (PMID 40161058, 2025). "Preoperative thyroid-related laboratory tests were all within normal ranges, including free triiodothyronine, serum free thyroxine, thyroid-stimulating hormone, anti-thyroid peroxidase antibody, anti-thyroglobulin antibody, and thyroglobulin levels." (PMID 41568262, 2025). "Thyroid antibodies, including anti-thyroglobulin antibody and anti-thyroid peroxidase (anti-TPO) antibody, were elevated." (PMID 40677481, 2025). "A family history of thyroid disorder (adjusted OR 4.12; p = 0.047) remained a significant determinant, and Anti-TPO antibody positivity independently predicted thyroid dysfunction (adjusted OR 6.78; p = 0.016)." (PMID 41473631, 2025). "The primary outcomes, including miscarriage, preterm birth, and postpartum thyroiditis, were analyzed in relation to TPO-Ab and TgAb levels." (PMID 41503315, 2025). "The LPS receptor, Toll-like receptor 4, is expressed in thyroid follicular cells, and LPS increases TPO (a major thyroid autoantigen) expression via the NF-κB pathway." (PMID 41170176, 2025). "Following the treatment, the T3, free-T4, and TPO Ab levels and thyroiditis status on ultrasound showed improvement." (PMID 38672958, 2024). "The diagnosis of AITD was made by the presence of thyroid-specific autoantibodies, mostly thyroid peroxidase antibodies (anti-TPO) in serum, and by varying degrees of thyroid dysfunction." (PMID 38297335, 2024). "In total, 64.5% developed a goiter, 46.0% exhibited thyroid heterogeneity on ultrasound, 23.4% had positive Anti-Tg, and 25.4% had positive anti-TPO autoantibodies." (PMID 39061665, 2024). "This is supported by a randomized controlled study that showed a significant reduction in postpartum thyroiditis when supplemental Se was administered to healthy pregnant women who were positive for TPO-Ab." (PMID 38281927, 2024). "Polyclonal TPOAb, mainly of IgG1 and IgG4 varieties, are directed towards the same TPO epitopes in normal individuals and thyroid disease." (PMID 39770919, 2024). "Maternal thyroid function test abnormalities, including subclinical hypothyroidism, isolated hypothyroxinemia, and thyroid peroxidase antibody positive, have been shown to increase the likelihood of premature birth." (PMID 39575054, 2024). "As a result of the presentation of thyroid antigens released by tissue destruction to the immune system, antithyroglobulin (anti-Tg) and antithyroid peroxidase antibodies (anti-TPO) are released into the circulation, which are helpful in diagnosis." (PMID 39230146, 2024). "There was not a statistically significant change in the number of patients that presented at least one positive autoantibody for thyroiditis (anti-TG or anti-TPO, p = 0.06) or type 1 diabetes (anti-IAA, anti-IA2, anti-Zn-T8, or anti-GAD, p = 0.15)." (PMID 38892641, 2024). "Anti-thyroid antibodies, such as anti-thyroid peroxidase (anti-TPO) antibodies, should be measured as part of the laboratory work for AITDs." (PMID 38256549, 2024). "Our findings suggest that there is a genetic relationship between the CTLA-4 (+55A/C) genotype and the seropositivity against thyroid autoantigens, such as anti-thyroid peroxidase (ATPO) and anti-thyroglobulin antibodies (ATG)." (PMID 37568880, 2023). "The patient's thyroid autoantibodies were tested positive at the time of thyroiditis with a TPO antibody of >900 and a thyroglobulin antibody of 1:20." (PMID 38259857, 2023).